SNORA40C (small nucleolar RNA, H/ACA box 40C)
Gene: Small nucleolar RNA gene on chromosome 6 (110,848,546 to 110,848,673, forward strand). Ensembl gene ENSG00000212587.
Gene Ontology:
Biological process: RNA processing
Cellular component: nucleolus
Homologues: Orthologues: chimpanzee SNORA40C (97% identical), macaque SNORA40C (91% identical). Paralogues in human: SNORA40B (95% identical), SNORA40 (92% identical).